RNU6-633P (RNA, U6 small nuclear 633, pseudogene)
Gene: Small nuclear RNA gene on chromosome 16 (10,496,272 to 10,496,374, forward strand). Ensembl gene ENSG00000199482.
Homologues: Orthologues: chimpanzee U6 (98% identical), macaque U6 (93% identical), mouse Gm24612 (93% identical). Paralogues in human: RNU6-1181P (94% identical), RNU6-12P (91% identical), RNU6-13P (91% identical), RNU6-16P (91% identical), RNU6-32P (91% identical), RNU6-393P (91% identical), RNU6-41P (91% identical), RNU6-945P (91% identical), RNU6-1 (90% identical), RNU6-1060P (90% identical), RNU6-116P (90% identical), RNU6-15P (90% identical), and 1286 more.